BRAF (B-Raf proto-oncogene, serine/threonine kinase)
Diseases named in the same sentence as BRAF in open-access papers (continued):
Sharing a sentence is not in itself a finding about the gene and the disease.
melanoma (continued). "We aim to investigate the efficacy of neoadjuvant plus adjuvant combined or sequenced vemurafenib, cobimetinib and atezolizumab in patients with high-risk, resectable BRAF-mutated and wild-type melanoma." (PMID 36845751, 2023). "A member of the RAF kinase family, BRAF mutations are common in many cancer types, including melanomas (60% occurrence), thyroid cancers (60%), colorectal cancers (15%), and non-small-cell lung cancers (5%–8%)." (PMID 37205232, 2023). "A combination of BRAF and MEK inhibitors is often used to treat metastatic BRAF-mutated melanoma and is associated with cardiotoxicity in 5% to 11% of patients." (PMID 37414756, 2023). "A mutation in the BRAF gene is present in approximately 50% of all melanomas in White populations and is a target of precision medicine, with the potential to dramatically improve patient outcomes." (PMID 36998456, 2023). "In this study, we report a model of acquired PLX4032 resistance obtained by chronically treating patient-derived BRAF-mutated melanoma cells with PLX4032." (PMID 37534247, 2023). "The combination of S63845 and vemurafenib has been previously shown to further decrease cell viability in BRAF-mutated melanoma cell lines." (PMID 36902392, 2023). "This is the first trial using phenformin in combination with RAF/MEK inhibition in patients with BRAF V600-mutated melanoma." (PMID 37930123, 2023). "Vemurafenib was identified as a selective inhibitor of BRAFV600E more than a decade ago, and has been proven to work effectively in BRAF mutated melanoma, although resistance to Vemurafenib develops rapidly." (PMID 37627277, 2023). "A patient in her late 60s presented with a BRAF V600E mutated melanoma with lymph node and brain metastases." (PMID 37728439, 2023). "BRAF mutations are frequently acquired in various malignancies including thyroid carcinoma, colorectal cancer and especially melanoma." (PMID 37834222, 2023). "Currently, the optimal treatment scenario for advanced melanoma patients depends on the mutation status of BRAF." (PMID 37895015, 2023). "The cytotoxic effect of G18.EE and G18.EE-n-BuOH was evaluated against the A375 BRAF-mutated human melanoma cell line through the sulforhodamine B (SRB) assay." (PMID 37049869, 2023). "The substitution of valine with glutamate at codon 600 (V600E) accounts for approximately 90% of the BRAF mutations in melanoma, resulting in constitutive kinase activity and unregulated cell proliferation." (PMID 37205993, 2023). "The ethanol extract of propolis from Gerês collected in 2018 (G18.EE) and its n-BuOH fraction (G18.EE-n-BuOH) were effective in decreasing cell biomass of the BRAF-mutated A375 melanoma cell line in a dose-dependent manner." (PMID 37049869, 2023). "Among the different melanoma subtypes, BRAFi benefits cutaneous melanomas the most, as they have the highest frequency of BRAF V600 mutations." (PMID 37239381, 2023). "A better understanding of the underlying oncogenic drivers in melanoma lead to the advent of targeted therapies, which, to date, have shown the best results in BRAF-driven cases." (PMID 37830586, 2023). "Somatic variant calling using exome sequencing of the nevus (Sample 1 - I) and the adjacent melanoma (Sample 1 - II) along with a matched normal sample, identified the BRAF V600E mutation as a driver mutation present in both the nevus and melanoma." (PMID 37932252, 2023). "High levels of CYTL1 are a poor prognostic factor for melanoma patients and can also be a potential therapeutic target for BRAF-mutated melanoma." (PMID 37745303, 2023). "In the present work, three BRAF-mutated human melanoma cell lines are tested for their sensitivity to HPF administration." (PMID 36674794, 2023). "Interesting, however, the IC50 of dabrafenib in BRAF-mutated hGBM8 cells was much higher than in the canonical A375 melanoma cell line (IC50 = 0.001 μM) used in previous studies." (PMID 37140883, 2023).
melanoma (continued). "In conclusion, GP-2250 has anti-neoplastic effects in BRAF-mutated melanoma cell lines regarding tumor cell viability, proliferation, and apoptosis/necrosis." (PMID 37895015, 2023). "In melanoma, the oncogenic mutation of BRAF promotes metabolic reprogramming, thereby often favouring glycolysis for energy production." (PMID 37495601, 2023). "Between 35 and 50 percent of melanomas have active BRAF mutations, which encourage tumor growth via the MAPK/ERK signaling pathway." (PMID 37745303, 2023). "On the other hand, numerous studies have identified specific miRNAs useful to monitor the responsiveness of BRAF-mutated melanoma patients to therapies." (PMID 37627054, 2023). "V600E/K mutations of the Raf family member BRAF are frequently found in melanoma and other solid tumor types for which the MAPK blocking agents dabrafenib and trametinib, inhibitors of BRAF and Mek, respectively, are used clinically in combination." (PMID 36768967, 2023). "The discovery of the BRAF mutation in half of all melanoma cases and the creation of small-molecule BRAF kinase inhibitors like vemurafenib revolutionized the treatment of melanoma." (PMID 37366925, 2023). "For example, PTEN (an important negative regulator of the PI3K pathway) in melanoma is frequently mutated/deleted and its loss of function is present and concomitant with BRAF mutations in approximately 44% of melanomas." (PMID 36835424, 2023). "In the phase II KEYNOTE-002 study, patients with ipilimumab-refractory melanoma were randomized to pembrolizumab or investigator choice chemotherapy, and the patients with BRAF V600-mutated were treated with BRAF inhibitor." (PMID 36995534, 2023). "To study the role of TERT in resistance to BRAFi and MEKi in BRAF-mutated melanoma, we overexpressed TERT in the BRAF-mutated melanoma cell line SkMel28, which expressed a low level of TERT due to a mutation at −57 bp in the TERT promoter." (PMID 37296851, 2023). "Our results provide novel insights into the effect of BRAF mutation on melanoma growth and indicate a promising direction toward immunotherapy and precision medicine in melanoma patients." (PMID 37205993, 2023). "MALAT1-ASO treatment strongly impaired cell growth and colony formation in a large panel of NRAS- and BRAF-mutated melanoma cells, including MEKi-resistant cells." (PMID 37235843, 2023). "Approximately 40% to 60% of melanoma patients have activated BRAF mutations and the most common mutation is found at amino acid 600, in which valine is replaced by glutamic acid (BRAFV600E)." (PMID 37049869, 2023). "Metalloproteinases (MMPs) and several cytokines/chemokines secreted by BRAF-mutated melanoma cells influence TME and alter the behavior of CAFs, that collaborate to support an immunosuppressive environment." (PMID 37627054, 2023). "The melanoma genome is highly mutated, with the most common mutation associated with the BRAF gene, a part of the mitogen-activated protein kinase (MAPK) signalling pathway." (PMID 37049869, 2023). "This variant accounts for 70–88% of BRAF-positive melanomas and it is a missense variant consisting of a substitution of valine with glutamic acid." (PMID 37627054, 2023). "BRAF mutated tumors still remain the only melanoma subtype that is treated with an approved targeted therapy." (PMID 38008717, 2023). "Here, we demonstrate that the combination of S63845 and the ERK inhibitor SCH772984 resulted in an impressive enhancement of the antitumor effects, both in BRAF-mutated and BRAF-WT melanoma cells." (PMID 36902392, 2023). "At the RNA level, RNA cantilevers enable the detection of genes and mutations, such as BRAF mutations in melanoma cells, or antimicrobial resistance genes in bacteria." (PMID 36817961, 2023). "Overall, BRAF mutation prevalence in human cancers is almost 100% for hairy cell leukemia, 50% for melanoma, 45% for papillary thyroid cancer, 10% for colon cancer, and 10% for non-small cell lung cancer cases." (PMID 37892237, 2023).
melanoma (continued). "BRAF V600-mutated melanomas can be treated with BRAF/MEK inhibitors, with response rates higher in V600E-mutated cases compared to V600K-mutated cases." (PMID 37958863, 2023). "Out of 462 melanoma samples, 322 (69.7%) were positive for Tier I/II variant and 8 patients had variants in two genes (5 patients with BRAF and NRAS; 3 patients with BRAF and KIT)." (PMID 37483495, 2023). "Collectively, these results indicate that, although STAG2 knockdown activates ERK signaling in both BRAF-mutant thyroid cancer cells and melanoma cells, it causes distinct cellular response to MEK inhibitor." (PMID 37479689, 2023). "Collectively, these results suggest that in a subset of melanoma cells, chronic BRAF inhibitor treatment can cause epigenetic adaptation that involves PPARGC1A suppression and acquisition of aggressive melanoma traits." (PMID 37277330, 2023). "In BRAF-mutated melanoma, the combination of encorafenib and binimetinib showed outstanding response rates and overall survival." (PMID 38067230, 2023). "Taken together, these results suggest that SR-4835 requires a functional CUL4-RBX1-DDB1 ubiquitin ligase complex to inhibit the proliferation of BRAF-mutated melanoma cells." (PMID 38104154, 2023). "It has been suggested that BRAF V600E-mutated melanomas show an aggressive phenotype, also depending on their subcellular localization." (PMID 37627054, 2023). "BRAF V600E has been implicated in multiple malignancies, including melanoma, colorectal cancer, hairy cell leukemia, and multiple myeloma." (PMID 37895447, 2023). "Combination therapy using encorafenib and binimetinib has also demonstrated favorable efficacy in patients with advanced melanoma with a mutation in BRAF V600, leading to its approval worldwide." (PMID 36355316, 2023). "The relationship between BRAF mutational status and different clinicopathological parameters was assessed in melanoma cases using the chi-square test after exclusion of cases that failed PCR analysis (3 cases)." (PMID 36737739, 2023). "This BRAF variant, in the past also referred to as V599E, is detectable in about 60% of human melanomas and activates MEK as a part of the mitogen-activated protein kinase (MAPK) pathway." (PMID 35202309, 2022). "Given the high effectiveness of both targeted therapies and immunotherapies, the combination of these drugs as an effective weapon for patients with melanoma BRAF V600-mutated was a logical consequence." (PMID 35742834, 2022). "BRAF-mutated melanomas often undergo metabolic changes toward aerobic glycolysis to supply their demands for growth and division." (PMID 36555289, 2022). "Additional roles for downstream mediators of RAS signaling were demonstrated in melanoma, where BRAF mutations conferring constitutive activation are often present." (PMID 36106023, 2022). "Mutations are frequently seen in the NRAS proto-oncogene (NRAS; 28%) and BRAF (52%) genes, and 80% of BRAF-mutated melanomas display the BRAFV600E mutation." (PMID 36084109, 2022). "Taken together, our study showed that ascorbate should be a potent and well-tolerated additional treatment option for patients afflicted with BRAF mutated melanoma." (PMID 35406796, 2022). "Approximately 40% of melanoma patients harbor a BRAF V600 driver mutation, making them attractive targets of BRAF and MEK inhibitors upon immunotherapy failure." (PMID 35790709, 2022). "Melanoma BRAF V600K at least accounts for 10% of all BRAF mutated melanomas, being the second more common genotype after V600E." (PMID 35160279, 2022). "Previous studies have documented how the use of a MAP2K2 inhibitor for BRAF-mutated melanoma triggers the PI3K/AKT pathway and leads to drug treatment resistance, although acquired MAP2K2 mutations have also been associated with the drug resistance." (PMID 35215249, 2022).
melanoma (continued). "Point mutation of BRAF by the substitution of valine to glutamic acid at codon 600 (V600E) occurs frequently (more than 50%) in melanoma than other types, which leads to a downstream MAPK pathway." (PMID 36135270, 2022). "Focusing on only regions of melanoma, they then tested the efficacy of three published BRAF mutation prediction classifiers." (PMID 36551716, 2022). "MEK162 is also evaluated in combination with third generation cyclin dependent kinases 4 and 6 (CDK4/6) inhibitor, Ribociclib (LEE001), showing increased antitumour activity and safety in advanced NRAS and BRAF mutated melanoma." (PMID 35993275, 2022). "Modern therapy of advanced melanoma offers effective targeted therapeutic options in the form of BRAF plus MEK inhibition for patients with BRAF V600 mutations." (PMID 35380338, 2022). "In fact, high secretion of IL‐6 has been associated with increased invasive migration in BRAF inhibitor‐resistant melanoma." (PMID 36176603, 2022). "Dabrafenib with trametinib has also been recommended for adjuvant treatment of adults with resected stage III BRAF V600 mutation-positive melanoma." (PMID 35559986, 2022). "Encorafenib, the most recent BRAF inhibitor for advanced V600-mutated melanoma, was approved by the FDA in June 2018." (PMID 35954441, 2022). "Melanoma has long been a poster child for personalized medicine with targeted therapies such as the BRAF inhibitors and the BRAF-MEK inhibitor combination being highly effective against the 50% of melanomas with activating BRAF mutations." (PMID 36139469, 2022). "Another noteworthy cross-resistance event between unrelated drugs that deserves mention, has been reported between the BRAF inhibitor vemurafenib and dacarbazine chemotherapeutic in a patient-derived BRAF-mutated melanoma cell model." (PMID 35814399, 2022). "BRAF mutation is an important driver of mutation in melanoma; therefore, BRAF inhibitors have been used to treat metastatic melanoma and recurrent melanoma with BRAF mutation." (PMID 35997352, 2022). "Binimetinib is a MEK inhibitor approved for the management of metastatic or BRAF V600E-mutated unresectable melanoma at the dosage of 45 mg twice a day in combination with encorafenib." (PMID 35742834, 2022). "In the mucosal melanoma dataset, 4.1% of patients had BRAF mutations, predicting sensitivity to BRAF inhibitors." (PMID 35849877, 2022). "A vast majority of BRAF V600E mutated melanoma patients will develop resistance to combined BRAF/MEK inhibition after initial clinical response." (PMID 35327519, 2022). "This clinical tumor sample was obtained from a patient with BRAF V600-mutated melanoma who was treated with BRAF and MEK inhibitors and developed a metastatic lesion with acquired resistance coincident with the acquisition of ecDNA." (PMID 36253572, 2022). "Clinical studies using a variety of MEK inhibitors, including trametnib, cobimetinib, and CI 1040 (PD184352), have shown that some melanomas, particularly those with BRAF mutations, reduce size." (PMID 35884733, 2022). "DNA of primary and recurrent tumor samples from 327 melanoma patients was used for identification of BRAF mutations." (PMID 36143252, 2022). "It is interesting to examine the rate of concordance of BRAF mutation amongst initial and new primary melanomas, in patients on immunotherapy." (PMID 35188271, 2022). "For neoantigen peptides, the “KIGDFGLATEJ” peptide produced by BRAF V600E mutation was frequently observed in four melanoma datasets with frequency larger than 0.05 in each dataset." (PMID 36139377, 2022). "The v-Raf murine sarcoma viral oncogene homologue B1 (BRAF) is one of the best-studied oncogenic mutations in melanoma." (PMID 36135270, 2022). "It has been reported that the combination of BRAF and MEK inhibitors rapidly shrinks BRAF V600E-mutated melanoma, although almost all cases suffer recurrence due to drug resistance." (PMID 35847022, 2022).
melanoma (continued). "Studies have found that 10% of melanoma patients harboring a BRAF mutation have the V600K driver mutation, the second most common type behind V600E." (PMID 35954441, 2022). "Trametinib is a kinase inhibitor targeting MEK1 and MEK2, approved for the management of metastatic or BRAF V600E- or BRAF V600K-mutated unresectable melanoma or as adjuvant treatment at an oral dosage of 2 mg a day." (PMID 35742834, 2022). "The combination of BRAFis and MEK inhibitors (MEKi) has recently demonstrated prolonged survival in patients with advanced melanoma harboring activating BRAF mutations." (PMID 35383224, 2022). "In 2011, vemurafenib became the first FDA-approved drug to target melanoma with V600E mutations in BRAF." (PMID 35954441, 2022). "Mechanistically, human melanomas with BRAF and NRAS mutations facilitate MITF expression and upregulate the level of the transcriptional coactivator PGC1α." (PMID 36612059, 2022). "Clearly, at least in the Chinese population, BRAF mutations, which are frequent in melanoma and GCMN with a high risk of malignant transformation, cannot be used as a valid marker to predict malignant transformation." (PMID 36085074, 2022). "Representative cancer-related genomic information includes epidermal growth factor receptor (EGFR) mutation in non-small cell lung cancer (NSCLC), ABL1 gene recombination in chronic myelogenous leukemia (CML), and BRAF mutations in melanoma." (PMID 35893795, 2022). "The aim of the present study is to evaluate the cost-effectiveness of options for the treatment of patients with stage III/IV melanoma after resection who have a BRAF V600 mutation." (PMID 35059911, 2022). "The finding that so many melanomas harbor the BRAF-V600E mutation led to the development of the selective inhibitors of the oncogenic kinase, including Vemurafenib and Dabrafenib." (PMID 36009541, 2022). "In light of the AJCC melanoma guideline, BRAF mutations are frequent in CM patients and play a significant part in the development of CM." (PMID 35300397, 2022). "A BRAF mutation is the most frequent type of mutation in melanomas (40–50%) as well as a resulting aberrant MAPK pathway activation, cell cycle deregulation, and apoptosis inhibition." (PMID 35269787, 2022). "For example, activating mutations in EGFR are frequent in relapsed lung adenocarcinoma, BRAF is often mutated in melanoma, and PIK3CA is often mutated in various entities, including luminal breast cancer." (PMID 35625984, 2022). "In parallel, the association between BRAF mutation and rapid disease progression allowed for the development of BRAF inhibitors, which are one of the greatest developments in the field of melanoma treatment." (PMID 36232957, 2022). "More recently it was demonstrated that the addition of the immune checkpoint inhibitor atezolizumab to vemurafenib and cobimetinib can improve the progression free survival of melanoma patients with BRAF V600E mutations." (PMID 36275468, 2022). "Both A375 and RPMI-7951 cells carrying a BRAF mutation were found at high frequencies in malignant melanoma." (PMID 35669782, 2022). "BRAF mutations frequently occur in melanoma, thyroid adenocarcinoma, colon carcinoma, gallbladder carcinoma, ovary cancer, and lung carcinoma." (PMID 36539659, 2022). "Pending the results of ongoing randomized studies, real word data can help to answer the question about the optimal strategy to choose as first line treatment in BRAF mutated stage IV melanoma patients." (PMID 36046043, 2022). "It was demonstrated that melanoma patients with BRAF mutation show some short-term advantage after targeted treatments (e.g., MAPK inhibitors)." (PMID 35628540, 2022). "BRAF is mutated in up to 60% of melanomas and most of these are activating BRAFV600E or BRAFV600K mutations." (PMID 35903549, 2022). "BRAF inhibitors have been demonstrated to induce autophagy in melanomas bearing BRAF mutations, which provoke tumor proliferation and resistance to chemotherapy." (PMID 36009363, 2022).